MTOR (mechanistic target of rapamycin kinase)
Diseases named in the same sentence as MTOR in open-access papers (continued):
Sharing a sentence is not in itself a finding about the gene and the disease.
pancreatic cancer (continued). "Proliferative markers such as phosphorylated forms of AKT, PI3K, mTOR, and p70S6K were significantly down–regulated in the pancreatic cancer cell lines treated with 25μM gedunin." (PMID 26988754, 2017). "Our results also verified that the activity of PI3K/Akt and mTOR signaling pathways increased after gemcitabine treatment, and the stemness of pancreatic cancer decreased after treated with PI3K/Akt and mTOR inhibitors combined with gemcitabine respectively." (PMID 29018223, 2017). "Other reports using rapamycin, an mTOR inhibitor, on pancreatic cancer cells and metformin on NSCLC cells have also revealed differential effects on Akt and Erk activation, thus indicating a feedback mechanism involving mTOR and RTK signaling." (PMID 28193239, 2017). "It has been reported that MEK inhibitors, U0126 and PD0325901, abrogate BEZ235-induced (a PI3K/mTOR dual inhibitor) ERK activation in KRAS mutant pancreatic cancer cell lines." (PMID 28574828, 2017). "The combination of TQ and gemcitabine contributes to increasing apoptosis and inhibiting tumor growth in pancreatic cancer via inactivation of Akt/mTOR/S6 signaling pathways by up-regulation of PTEN." (PMID 29156767, 2017). "Biopsies of human pancreatic cancer cells obtained through endoscopic ultrasonography that overexpressed pS6 (a downsteam effector activated by mTOR overexpression) show sensitivity to ­rapamycin inhibition ex vivo." (PMID 27200288, 2016). "Taken together, our findings demonstrate that HS-173 can efficiently suppress EMT and metastasis by inhibiting PI3K/AKT/mTOR and Smad2/3 signaling pathways, suggesting it can be a potential candidate for the treatment of advanced stage pancreatic cancer." (PMID 27793006, 2016). "The chemokine CXCL12 binds the two receptors CXCR4 and CXCR7 and transduces on the mTOR pathway in pancreatic cancer, gastric cancer, T cell leukemia cell and in human renal cancer cells." (PMID 26934559, 2016). "Analysis of downstream targets in pancreatic cancer cell lines identified that MEK/ERK/TSC/mTOR signaling is dependent on ALDH1A3 function and high expression of ALDH1A3 is associated with an aggressive subtype of PDAC." (PMID 27200288, 2016). "Second, the ability of metformin to inhibit the mTOR pathway in pancreatic cancer also appears to be only partially AMPK-dependent." (PMID 26760500, 2016). "To provide a robust therapeutic approach against the resistant cell population such as PANC 1 cells, we tried the combination treatment of pancreatic cancer cells with the mTOR inhibitor rapamycin." (PMID 27349387, 2016). "Rottlerin induced apoptosis and autophagic cell death in prostate and pancreatic cancers via the inhibition of PI3K/Akt/mTOR signaling." (PMID 26999089, 2016). "This is in accordance with the recently described lower mTOR control over TFEB in pancreatic cancer cells." (PMID 27268034, 2016). "Based on these results, we investigated the efficacy of combination treatment of GANT61 and the mTOR inhibitor (rapamycin) to pancreatic cancer cell lines." (PMID 27349387, 2016). "Primary and transformed pancreatic cancer cells exhibit a concentration- and time-dependent arrest of growth upon dual mTOR inhibition with INK-128 via 4E-BP1, S6K1, and AKT." (PMID 27200288, 2016). "Combined treatment with metformin and rapamycin of Panc02 cells transplanted into diet-induced obese (DIO) C57BL/6 mice lead to significantly reduced pancreatic tumor growth and mTOR-related signaling." (PMID 27200288, 2016). "Analysis of key molecules involved in the induction of proliferation by immunoblots revealed that nimbolide treatment reduced the expression levels of the phosphorylated forms of AKT, PI3K, ERK, mTOR and p70S6 kinase in the pancreatic cancer cell lines;." (PMID 26804739, 2016). "MiR-99b was described to contribute to irradiation resistance in human pancreatic cancer by targeting mTOR, whose activity is also known to play a role in NAFLD-NASH." (PMID 26728044, 2016).
pancreatic cancer (continued). "We determined miR-99b levels as it is known to target mTOR mRNA and confer resistance to radiation in human pancreatic cancer cell lines." (PMID 27421140, 2016). "There is increasing evidence that mTOR activation is a common event in the development of various pancreatic tumors such as PDAC, a subset of cystic tumors and pancreatic neuroendocrine tumors (PNETs,)." (PMID 26683340, 2015). "In summary, our findings suggest that combined inhibition of PI3K/Akt/mTOR and Shh pathways will be beneficial for the treatment of pancreatic cancer by targeting CSCs, and further study of these pathway inhibition in the clinical setting is warranted." (PMID 26451606, 2015). "Here we investigate the effects of a constitutively active PI3K in the pancreas and examine the response of PIK3CA mutant pancreatic cancer to dual PI3K/mTOR inhibition." (PMID 26436951, 2015). "We have further revealed that HNF1A knockdown activates Akt/mTOR signaling pathway in pancreatic cancer cell lines." (PMID 25793983, 2015). "Here we examine mutant PIK3CA-mediated pancreatic tumorigenesis and the response of PIK3CA mutant pancreatic cancers to dual PI3K/mammalian target of rapamycin (mTOR) inhibition." (PMID 26436951, 2015). "The constitutive activation of AKT/mTOR has been involved in the pathogenesis and progression of pancreatic cancer." (PMID 25793983, 2015). "We are grateful to Prof. Aldo Scarpa for providing us with the pancreatic cancer cell lines and Dr. Lucia Anna Muscarella for providing us the antibodies for mTOR pathway." (PMID 26176887, 2015). "This need is underscored by a recent report that in pancreatic cancer inactivation of PI3K/mTOR signaling led to compensatory increase in mitogenic MEK/ERK signaling." (PMID 26497569, 2015). "In our study, AZD8055, an mTOR inhibitor, significantly decreased the phosphorylation of S6K, resulting in repression of the expression of Mcl-1 in the two pancreatic cancer cell lines." (PMID 26056043, 2015). "The compound alone or in combination with rapamycin, an mTOR inhibitor, showed significant growth inhibition in murine xenograft models of human pancreatic cancer cells OCIP19, 21, and 23 mediated by cell cycle arrest predominantly in G1 phase." (PMID 26369833, 2015). "We further demonstrated that HNF1A knockdown activated Akt and its downstream target, the mammalian target of rapamycin (mTOR) in pancreatic cancer cells." (PMID 25793983, 2015). "Clinical trials of mTOR inhibitors in advanced pancreatic cancer have, thus far, have been preformed in unselected patients." (PMID 24717934, 2014). "Metformin's antitumor effects, however, occur without stimulating Akt and ERK activation, and therefore, metformin in combination with mTOR inhibitors represents a future direction to improve clinical efficacy in pancreatic cancer." (PMID 25426078, 2014). "Anti-proliferative; cytotoxic to pancreatic cancer cells via PI3K/Akt/mTOR inhibition; inhibits NF-κB; STAT and amyloid aggregation." (PMID 24833337, 2014). "Another mechanism which can account for the inefficacy of mTOR inhibitors in pancreatic cancer has been recently highlighted." (PMID 25594050, 2014). "One key signaling pathway that is frequently over-activated in pancreatic cancer is Akt/mTOR signaling cascade, which is responsible for cancer cell survival, proliferation, apoptosis-resistance, migration and metastasis." (PMID 24886166, 2014). "In the present study, we demonstrate that PM inhibits proliferation and induces apoptosis in pancreatic cancer cells by inhibiting the pro-survival Akt, NF-κB and mTOR signaling proteins and their downstream mediators as well as anti-apoptotic Bcl-2." (PMID 24603988, 2014). "Collectively, these findings imply that mTOR signaling plays an important role in obesity-induced pancreatic cancer and is a potential target for chemoprevention." (PMID 25295009, 2014).
pancreatic cancer (continued). "Here, we examined the effects of KLT on the PI3K/Akt/mTOR pathway in pancreatic cancer xenografts in mice, and assessed its therapeutic potential." (PMID 25005526, 2014). "As previously stated, high levels of mTOR activity support proliferation and survival of pancreatic cancer cells, and CR consistently results in decreased activation of mTOR in pancreatic tumors." (PMID 24685128, 2014). "Together, these data indicated that induction of apoptosis in pancreatic cancer cells by PM involves the inhibition of pro-survival p-Akt, NF-κB and mTOR and their downstream mediators as well as PKCɛ mediated pathway of apoptosis." (PMID 24603988, 2014). "In the present study, we tested the effect of leucine supplementation on transplanted Panc02 mouse pancreatic cancer growth and mTOR signaling in the context of lean mice (fed a CR diet regimen) or overweight mice (fed a high calorie control diet regimen)." (PMID 24685128, 2014). "In the current study, everolimus showed time-dependent anti-proliferative and pro-apoptotic effects in Panc-1 human pancreatic cancer cells, possibly by inhibiting mTOR signaling." (PMID 23251295, 2013). "The EGFR/MAPK and PI3K/Akt/mTOR pathways are often dysregulated and considerable evidence supports the important role of these pathways in the biology of pancreatic cancer." (PMID 22367239, 2013). "This is the first report to demonstrate changes in the phosphorylation of mTOR effectors in pancreatic cancer stem-like cells by immunoblotting." (PMID 24231729, 2013). "All these data collectively demonstrate that radiation induced mTOR expression and activation contributes to radioresistance and knockdown of endogenous mTOR effectively overcomes the radioresistance of pancreatic cancer cells." (PMID 23886294, 2013). "Collectively, ionizing radiation significantly induces mTOR expression and activation at mRNA as well as protein levels, which possibly contribute to radioresistance in pancreatic cancer." (PMID 23886294, 2013). "Mutation of K-Ras, the predominant mutation in pancreatic cancer, leads to aberrant activation of Erk in pancreatic cancer cells, which in turn leads to mTOR activation." (PMID 23667692, 2013). "In summary, our study observed mTOR upregulation in clinically treated biopsy samples and identify a novel mechanism related with mTOR upregulation in pancreatic cancer cells after radiation therapy." (PMID 23886294, 2013). "An inhibitory effect of metformin on the phosphorylation of mTOR, which has been reported in cancer cells including those of pancreatic cancer, was observed in CD133+ pancreatic cancer cells in this study." (PMID 23667692, 2013). "Taken together, these findings demonstrate that rapamycin inhibits sphere formation in three pancreatic cancer cell lines, confirming that the mTOR pathway is important for stem-like cell functions." (PMID 24231729, 2013). "All the data collectively demonstrated that blockage of radiation-induced aberrant mTOR expression and phosphorylation significantly sensitized pancreatic cancer cells to radiation and acquired increased anti-tumor activity in vivo." (PMID 23886294, 2013). "Ionizing radiation promoted mTOR expression and activation in pancreatic cancer cells through reducing miR-99b expression, which negatively regulated mTOR." (PMID 23886294, 2013). "Here, we report that inhibiting the mTOR pathway suppressed the growth of CD133-expressing (CD133+) pancreatic cancer cells and reduced pancreatic cancer cell sphere formation under stem cell culture conditions and colony formation in soft agar." (PMID 24231729, 2013). "Our data provide a rationale for overcoming radio-resistance by combined with mTOR inhibitor AZD8055 in pancreatic cancer therapy." (PMID 23886294, 2013). "Here, we demonstrate that treatment of PANC-1 or MiaPaCa-2 pancreatic cancer cells with either rapamycin or active-site mTOR inhibitors suppressed S6K and S6 phosphorylation induced by insulin and the GPCR agonist neurotensin." (PMID 23437362, 2013).
pancreatic cancer (continued). "In the present study, we investigated the significance of the mTOR pathway in maintaining the properties of pancreatic cancer stem cells." (PMID 24231729, 2013). "mTOR signaling is abnormally upregulated in multiple types of cancers and has been explored as a potential therapeutic target in patients with pancreatic cancer." (PMID 23251295, 2013). "To further ascertain the role of the mTOR pathway in the self-renewal of pancreatic cancer stem-like cells, we analyzed another pancreatic cancer cell line, PANC-1." (PMID 24231729, 2013). "It was observed that the mTOR pathway functions to maintain the properties of stem-like pancreatic cancer cells." (PMID 24231729, 2013). "Blockade of mTOR by AZD8055 represents a new therapeutic strategy to overcome radioresistance in patients with pancreatic cancer." (PMID 23886294, 2013). "miR-99b reduction was involved in mTOR upregulation and therefore affected the radiotherapy sensitivity of pancreatic cancer cells." (PMID 23886294, 2013). "In the present study, we focused on the mTOR pathway based on the results of our screening for potential agents effective against pancreatic cancer stem-like cells (see Results section)." (PMID 24231729, 2013). "Triptolide induces autophagy in pancreatic cancer cells and also inhibits the Akt/mTOR/p70S6K pathway." (PMID 22802963, 2012). "The purpose of this work was to determine the efficacy of inhibiting mammalian target of rapamycin (mTOR) in pancreatic cancer preclinical models and translate preclinical observations to the clinic." (PMID 20664591, 2010). "Agents targeting the ERK and mTOR pathway have anticancer activity in primary xenografts, and these results support testing this combination in pancreatic cancer patients." (PMID 20920162, 2010). "In spite of the complexity of inter-tumoural heterogeneity in the prediction of in vivo response, the combination of agents targeting the ERK and mTOR pathway has anticancer activity in primary pancreatic cancer xenografts." (PMID 20920162, 2010). "From these studies, we concluded that mTOR inhibitors exerted distinct anti-tumour effects in pancreatic cancer xenografts that were characterised by heightened activation of the PI3K/Akt/mTOR pathway." (PMID 20664591, 2010). "The PI3K/Akt/mTOR pathway is activated in pancreatic cancer by overexpression or activation of EGFR and insulin-like growth factor (IgF1R), by PTEN loss or secondary to k-ras mutation and activation of the Ras/Raf/MEK pathway." (PMID 20630061, 2010). "In this work, we followed such an approach to test the activity of mTOR inhibitors in pancreatic cancer." (PMID 20664591, 2010). "Here in this study, we demonstrate that HCCR-1 is responsible for pancreatic cancer via EGF mediated-PI3K/Akt/mTOR signaling pathway." (PMID 20423485, 2010). "Overall, these data indicated that Akt and mTOR are the molecular targets of CDDO-Me in pancreatic cancer cells." (PMID 21799944, 2010). "Our result shows that both LY294002 and rapamycin inhibit the up-regulation effect of HCCR-1 by EGF, suggesting that EGF-induced HCCR-1 expression is mediated by PI3K/mTOR signaling in pancreatic cancer." (PMID 20423485, 2010). "This study aimed to determine the therapeutic role of inhibiting mTOR in preclinical models of pancreatic cancer and in patients with this disease." (PMID 20664591, 2010). "Next, the expression and constitutive phosphorylation of molecules involved in the ERK and mTOR downstream signalling pathways in pancreatic cancer tissues were examined." (PMID 20920162, 2010). "In summary we have integrated a preclinical and clinical trial of mTOR inhibitors in pancreatic cancer." (PMID 20664591, 2010). "We recently reported on the effects of combined MEK and mTOR inhibition in vitro or in xenograft models established from pancreatic cancer cell lines." (PMID 20920162, 2010).
pancreatic cancer (continued). "Inhibition of mTOR is therefore being explored as an anti-cancer strategy for several types of human malignancies, including pancreatic cancer." (PMID 20630061, 2010). "The mTOR inhibitor, temsirolimus, induced tumour regressions in 4 of 17 (23%) freshly generated pancreatic cancer xenografts that were, in conjunction, characterised by genetic alterations, leading to an increased activation in the PI3K/Akt/mTOR pathway." (PMID 20664591, 2010). "It suggests that HCCR-1 is one of the down-stream components of the EGF-triggered PI3K/Akt/mTOR signaling which plays a pivotal role in the pancreatic cancer tumorigenesis." (PMID 20423485, 2010). "The phosphoinositide 3-kinase (PI3K)/Akt pathway is constitutively activated in pancreatic cancer and the mammalian target of rapamycin (mTOR) kinase is an important mediator for its signaling." (PMID 20630061, 2010). "Selective inhibition of Akt or mTOR with gene-specific siRNA increased the sensitivity of pancreatic cancer cells to CDDO-Me at concentrations which were otherwise inactive." (PMID 21799944, 2010). "Our recent studies revealed that mTOR inhibitors such as rapamycin and temsirolimus increase Akt phosphorylation/activation and cyclin D1 expression levels in pancreatic cancer cells." (PMID 20630061, 2010). "Furthermore, immunostaining of pancreatic cancer tissues from each group revealed a 52% decrease in the expression of p-mTOR in tissues from KPC/ Slc25a20+/- mice compared to KPC mice." (PMID 40521210, 2025). "Notably, silencing of Akt or mTOR using gene-specific siRNA enhanced the sensitivity of pancreatic cancer cells to bardoxolone methyl, indicating that these pathways are critical targets for its antiproliferative and pro-apoptotic activity." (PMID 40732256, 2025). "For example, HMGA2 mediated the occurrence of triple-negative breast cancer by activating the NF-kB/IL-6/IL-8/STAT3 axis; HMGA2 activated the mTOR signaling pathway to inhibit ferroptosis, thereby enhancing the death resistance of pancreatic cancer and reducing chemotherapy sensitivity." (PMID 40703517, 2025). "Similarly, AZD-8055, an mTOR inhibitor, is under investigation for its potential role in treating various cancers, including pancreatic tumors." (PMID 40301300, 2025). "Collectively, these data suggested that the apoptotic effect of AZD5153 in combination with GEM may be mediated by the inhibition of ERK/mTOR signaling in pancreatic cancer cells." (PMID 40859234, 2025). "The PI3K/Akt/mTOR signaling pathway is a critical regulator of cancer hallmarks, including cell survival, proliferation, metabolism, and metastasis, and is frequently activated in pancreatic cancer." (PMID 40648084, 2025). "Although AZD8055 was initially able to inhibit the activity of mTOR complexes 1/2 and the Akt signaling pathway, this inhibition was only transient; pancreatic cancer cells rapidly regained tolerance to the drug with the activation of EGFR and its downstream kinases." (PMID 40125551, 2025). "However, the efficacy of mTOR inhibitors such as everolimus and ridaforolimus in pancreatic cancer remains controversial." (PMID 40994638, 2025). "However, in pancreatic cancer, resistance has been attributed to compensatory activation of the mTOR and MEK/ERK pathways." (PMID 41262902, 2025). "Therefore, it has been confirmed that LDLRAD2 is involved in the progression of pancreatic cancer by regulating the AKT/mTOR pathway." (PMID 39349424, 2024).